GRPR (gastrin releasing peptide receptor)
Diseases named in the same sentence as GRPR in open-access papers (continued):
Sharing a sentence is not in itself a finding about the gene and the disease.
lung carcinoma (continued). "Gastrin-releasing peptide receptor (GRPR) is our target of interest for in vivo molecular imaging, as it is a biomarker overexpressed in many cancers, including prostate, breast, colon, and lung cancers." (PMID 36733960, 2023). "We observed a statistically significant association between GRPR expression in bronchial mucosa and smoking status among lung cancer patients (P = 0.03) with overrepresentation of GRPR bronchial expression among never smoking lung cancer patients." (PMID 22296774, 2012). "The association was found in both male and female never smokers, suggesting GRPR plays a similar role in development of lung cancer in men and women." (PMID 22296774, 2012). "While GRPR expression was detected in only a minority of never smoking cancer-free controls, GRPR expression was detected in almost 90% of never smoking lung cancer cases." (PMID 22296774, 2012). "We conclude from our data that GRPR expression likely does not contribute to sex differences in rates of lung cancer incidence in never or former smokers." (PMID 22296774, 2012). "Of special interest was the finding of frequent bronchial GRPR expression among never smoking lung cancer cases." (PMID 22296774, 2012). "The hazards ratio for overall lung cancer survival in Cox models adjusted for age, sex, and disease stage was 0.87 (95% CI = 0.57-1.34) for patients with GRPR bronchial expression compared to patients without detectable GRPR bronchial expression." (PMID 22296774, 2012). "Because we hypothesized that GRPR expression in bronchial epithelia would contribute to increased risk of lung cancer for women never smokers compared to men never smokers, we tested the interaction between sex and GRPR expression status for association with lung cancer in the never smoking stratum." (PMID 22296774, 2012). "Presence or absence of GRPR mRNA in non-cancerous bronchial epithelial cells derived from mainstem bronchus airway biopsies of lung cancer cases (n = 224) and cancer-free controls (n = 107) was assessed by RT-PCR followed by hybridization with a radio-labeled probe in order to maximize sensitivity." (PMID 22296774, 2012). "The GRPR pathway may activate proliferative pathways that increase the likelihood of lung cancer development in male and female former and never smokers." (PMID 22296774, 2012). "However, lung cancer cases positive for GRPR expression were statistically younger than GRPR negative cases." (PMID 22296774, 2012). "Alternatively, activation of the GRPR pathway may increase EGFR bronchial cell signaling in the absence of EGFR mutation, providing another route to lung cancer development in never smokers." (PMID 22296774, 2012). "However, the presence of GRPR mRNA in bronchial cells was not an indication of overall lung cancer survival." (PMID 22296774, 2012). "The findings revealed that GRPR could stimulate the breakdown of inositol phosphate, induce changes in intracellular calcium levels, increase MAPK phosphorylation, promote cell growth, trigger trans-activation of EGFR in specific lung cancer cell lines, and influence cell signaling and growth." (PMID 38279185, 2024). "High affinity NMBR (Ki = 0.15 nM) and moderate affinity GRPR (Ki = 1.0 nM) non-peptide antagonist PD176252 significantly inhibited NCI-H1299 proliferation (and was more potent than PD168368) and considerably inhibited lung cancer colony number in vitro." (PMID 29262666, 2017).
itch (21 papers, 2012 to 2025). "In this research, the cellular basis of itch sensation was explored and the GRPR was, for the first time, identified as a pruritus‐related specific receptor." (PMID 37902196, 2024). "Morphine is commonly used for pain relief but can induce pruritus, and studies have shown that morphine provokes itch by triggering the internalization of GRPR and mu-opioid receptor (MOR)-1D." (PMID 36597164, 2023). "Both spontaneous and CQ-evoked itch behaviours were suppressed when GRPR and NPY cells were silenced simultaneously, and we show directly, using both anatomical and electrophysiological methods, that the NPY cells provide a strong inhibitory input to GRPR-INs." (PMID 37490401, 2023). "Here the authors show that neuronal pentraxin 2 upregulated in primary sensory neurons in chronic itch models is required for facilitating excitatory synaptic inputs onto GRPR expressing spinal neurons." (PMID 35501343, 2022). "In this study, we investigate the glutamatergic excitatory synaptic responses in SDH GRPR+ neurons using animal models of chronic itch related to atopic and contact dermatitis." (PMID 35501343, 2022). "Here, we show that glutamatergic excitatory inputs onto GRPR+ neurons are facilitated in mouse models of chronic itch." (PMID 35501343, 2022). "We showed that optogenetic stimulation of spinal itch-selective GRPR+ neurons evoked intensity-dependent itch-like scratching behavior, similar to the chemical itch model." (PMID 35769233, 2022). "Further, using several genetic tools we elucidate the role of neuronal pentraxin 2 (NPTX2; also known as NARP), an activity-dependent immediate early gene product, in the facilitation of excitatory synaptic responses in GRPR+ neurons in chronic itch models." (PMID 35501343, 2022). "Together, these results suggest that innocuous touch and chemical itch information converge on GRPR neurons and thus map an exquisite spinal circuitry hard-wired for converting innocuous touch to irritating itch." (PMID 33033265, 2020). "In summary, we showed that SDH-projecting LC-NAergic neurons have an intrinsic potential to suppress acute and chronic itch and that NA facilitates inhibitory synaptic inputs onto GRPR+ SDH neurons presumably via α1A-ARs." (PMID 33109226, 2020). "The results presented here demonstrate the existence of a complex local inhibitory tone, composed of both synaptic and tonic currents that specifically regulates the excitability of GRPR neurons, neurons that are known to transmit itch." (PMID 31719558, 2019). "The GRP/GRPR system in the dorsal horn is suggested as a key component of a neuronal network that transmits itch-related information." (PMID 31719558, 2019). "Together, the present study not only improves the understanding of itch neurotransmission in the spinal cord but also lays out the pharmacological basis for the development of GRPr and NMBr antagonists for the treatment of pruritus." (PMID 23826298, 2013). "GRPR knockout mice show normal thermal, mechanical, inflammatory, and pain responses, but reduced responses to pruritogenic stimuli, and GRP-induced pruritus in wild-type mice is blocked by intrathecal administration of a GRPR antagonist." (PMID 23251133, 2012). "Considering that our histological analysis demonstrated that both His and CQ instillation significantly increased the neural activity of the GRPR-expressing neurons in the Sp5C, it is possible that His-induced itch is indirectly involved in the activity of GRPR-expressing neurons." (PMID 38098939, 2023). "Under pathological itch conditions, lamina IIi Tac2 and laminae I–IIo GRPR neurons might be sensitized to convey heightened alloknesis, in part due to disinhibition, thereby exacerbating chronic itch conditions." (PMID 33033265, 2020).
itch (continued). "The findings show a complex inhibitory network, composed of synaptic and tonic currents that gates the excitability of GRPR neurons, which provides direct evidence for the existence of an inhibitory tone controlling spontaneous discharge in an itch-related neuronal network in the spinal cord." (PMID 31719558, 2019). "However, recent studies suggested that both mechanical and chemical pruritus brought about by light touch can converge on spinal GRPR neurons transmitting to the center, so GRPR may be the integration point of various pruritic spinal pathways." (PMID 36597164, 2023). "The IL-31-induced pruritus is mediated by NKB and its receptor NK3R, and then by GRP and its receptor GRPR." (PMID 33924978, 2021). "Using this tool, we next analyzed mCherry+ SDH neurons that displayed delayed firing patterns (hereafter referred to as GRPR+ neurons) and examined whether excitatory synaptic inputs to GRPR+ SDH neurons are changed under chronic itch-like conditions." (PMID 35501343, 2022). "The data suggest that opioid-induced itch is an active process concomitant with but independent of opioid analgesia, occurring via the unidirectional cross-activation of GRPR signaling by MOR1D-GRPR heterodimerization." (PMID 23956775, 2013). "In addition, mice lacking GRPR, or those in which GRPR-expressing dorsal horn neurons are ablated, show reduced responses in several itch models." (PMID 32764601, 2020). "Also, we cannot completely rule out the possibility that the artificial manipulation of spinal GRPR+ neurons also elicited other types of sensory input, which could also contribute to the non-overlapping S1 responses between opto-itch and chloroquine sessions." (PMID 35769233, 2022). "Moreover, since the perception and motor output of acute chemical itch, dry skin itch and mechanical itch are identical, it is economic for spinal GRPR neurons to convert touch to itch rather than using a separate neural pathway for mechanical itch transmission." (PMID 33033265, 2020).
prostate tumors (19 papers, 2012 to 2025). "In this article, several preclinical studies using relevant xenograft models of GRPR-overexpressing prostatic tumors have demonstrated the benefits of [212Pb]Pb-DOTAM-GRPR1." (PMID 39327021, 2024). "With the ICG-PLGA nanobubbles, we demonstrated dual in vivo photoacoustic/ultrasound molecular imaging of gastrin-releasing peptide receptor (GRPR) expression in a mouse xenograft prostate tumor model." (PMID 36733960, 2023). "A recent study reported the effectiveness of gastrin-releasing peptide receptor (GRPR)-targeted 67Cu-SAR-BBN in PC-3 prostate tumor-bearing mice." (PMID 37345092, 2023). "GRPR expression is found in 63–100% of primary prostate tumors and in the majority of lymph node and bone metastases." (PMID 37175001, 2023). "An important characteristic of GRPR is that it is overexpressed in prostatic tumor cells, but only low levels of receptors were found on normal prostate tissues." (PMID 33672425, 2021). "GRPR was shown to be expressed in almost 100% of prostate tumors by PCR, immunohistochemistry, and radionuclide binding assays of clinical samples." (PMID 33335885, 2020). "In a similar way to PSMA, gastrin-releasing peptide receptor (GRPR) is also overexpressed in prostatic tumor cells while only low levels of receptors are found in normal prostate tissue." (PMID 31394799, 2019). "Our developed GRPR-targeted MRI contrast agents enable us for the first time to observe differential and heterogeneous distribution of GRPR expression levels in prostate tumor PC3 and lung tumor H441 models." (PMID 26577829, 2015). "Because GRPR is expressed in 63-100% of primary prostate tumors and over 50% of metastases, it presents an attractive target for both therapeutic and diagnostic applications." (PMID 24312607, 2013). "A range of molecules targeting both αvβ3 and the gastrin releasing peptide receptor (GRPR), which is highly expressed on androgen resistant prostate tumours, have been investigated." (PMID 24213501, 2012). "The observed intrapatient heterogeneity of GRPR and PSMA suggests that future theranostics for primary prostate tumors may benefit from an approach in which GRPR- and PSMA-targeting radiopharmaceuticals are combined." (PMID 37719014, 2023). "We then demonstrate that the designed GRPR-targeting reagent (ProCA1.GRPR) has the unique capacity to selectively enhance the MRI signal of xenografted prostate tumor depending on the expression levels of GRPR in vivo in mice due to its improved relaxivity, targeting capability and specificity." (PMID 26577829, 2015). "The GRPR expression level in human prostate tumors differs over time." (PMID 24312607, 2013). "Considering the high degree of heterogeneity among prostate tumors, it is unlikely that PSMA- or GRPR-targeting agents alone will be ideal in all clinical situations." (PMID 31540122, 2019). "The use of these radiotracers in the prostate indicating GRPR could help identify probably preneoplastic lesions (high grade PIN) and low grade prostate tumors with NED in cancer patients." (PMID 33854977, 2021). "Nevertheless, not differently than in many other GRPR-targeting projects, the typical accumulation region during this study turned out to be the pancreas (39.83 ± 2.76% injected activity at 1 h) as there are approximately seven times more GRPR sites to bind than in prostate tumor." (PMID 36834867, 2023).
neuroblastoma (14 papers, 2012 to 2025). Neuroblastoma (NB) is the most common solid, extracranial childhood tumor. "The silencing of AKT2 in cultured neuroblastoma cells resulted in decreased growth and decreased VEGF secretion in vitro, while Akt2-silenced xenografts in nude mice showed fewer liver metastases; therefore, Akt silencing caused the same results as knockout of GRPR in the neuroblastoma cells." (PMID 34539578, 2021). "In another study of 24 tumours, GRPR was expressed to a variable degree, with higher expression in more undifferentiated neuroblastoma." (PMID 40426729, 2025). "GRPR knockdown also inhibited neuroblastoma tumorigenicity by blocking colony formation in vitro and reducing xenograft development and liver metastasis in vivo." (PMID 34943797, 2021). "In almost all studies, selective GRPR antagonists inhibited cultured neuroblastoma cell line growth, as well as SK-N-SH xenograft growth in nude mice." (PMID 34539578, 2021). "Two studies provide evidence for an important role in GRPR activation in neuroblastoma cell lines for the PI-3K pathway in mediating the GRP-stimulated growth effects in these cells." (PMID 34539578, 2021). "Overexpression of the GRPR in a human neuroblastoma cell line (SH-SY5Y cells) markedly increased the basal growth rate." (PMID 34539578, 2021). "In contrast, the overexpression of the GRPR in less aggressive SK-N-SH neuroblastoma cells resulted in colony formation, which was inhibited by GRP-blocking antibody." (PMID 34539578, 2021). "In one study of 33 human neuroblastomas, 73% possessed GRPR by immunocytochemical studies, with increased expression in undifferentiated tumors compared to benign tumors." (PMID 34539578, 2021). "We have previously reported that gastrin-releasing peptide receptor (GRP-R) mediated tumor progression in neuroblastoma occurs via activation of the PI3K/AKT pathway." (PMID 31608140, 2019). "Furthermore, inhibition of PI-3K with wortmannin in neuroblastoma cells markedly decreased both GRPR mRNA levels and neurotensin receptor levels." (PMID 34539578, 2021). "Using PCR, GRPR mRNA was found in three human neuroblastoma cell lines (IMR-32, SK-N-SH, LAN-1)." (PMID 34539578, 2021). "However, in one study involving the murine neuroblastoma cell line Neuro2A, a low concentration (0.1 nM) of the selective GRPR antagonist RC-3095 inhibited cell growth, but with a higher concentration (100 nM), it stimulated growth." (PMID 34539578, 2021). "Furthermore, in a neuroblastoma xenograft study, a GRPR antagonist decreased the plasma VEGF levels, which correlated with a decreasing tumor size." (PMID 34539578, 2021). "In IMR-32 neuroblastoma cells, GRP did not stimulate changes in cytosolic calcium, although GRP stimulated growth, suggesting both Ca2+-dependent and -independent pathways may mediate the growth effects of GRPR activation in different neuroblastoma cells." (PMID 34539578, 2021). "The GRPR might also regulate the growth of neuroblastoma, although, in contrast, we could not find a role for GRPR in regulating the in vitro growth of medulloblastoma, the most common brain cancer of childhood." (PMID 23251133, 2012). "Gastrin-releasing peptide receptor (GRP-R) is a G protein-coupled receptor (GPCR) that is overexpressed on the membranes of dysplastic cells in numerous cancers, including neuroblastoma." (PMID 36525420, 2022). "Gastrin-releasing peptide receptor (GRP-R) is overexpressed in numerous malignancies, including poorly-differentiated neuroblastoma." (PMID 36525420, 2022). "GRP is reported to increase cytosolic calcium in neuroblastoma cell lines (SK-N-SH, LAN-2), and in LAN-1 neuroblastoma cells, the stimulation was inhibited by a specific GRPR antagonist." (PMID 34539578, 2021). "Gastrin-releasing peptide receptor (GRP-R) overexpression downregulated PTEN transcription and GRP treatment induces neuroblastoma cell cycle progression via PI3K/AKT." (PMID 24039782, 2013).
neuroblastoma (continued). "We have shown that gastrin-releasing peptide receptor (GRP-R), a G-protein coupled receptor, is involved in neuroblastoma cell survival, invasive potential and metastasis." (PMID 23211542, 2012). "The importance of PI3K mediating GRPR-stimulated growth in these cells was supported by the finding that LY294002, a PI3K inhibitor, suppressed the increased growth seen in GRPR-overexpressing neuroblastoma cells, as did overexpression of PTEN in these cells." (PMID 34539578, 2021). "Similarly, in binding studies in human neuroblastoma cell lines, in a study using 125I-GRP combined with GRPR-crosslinking, SK-N-SH neuroblastoma cells were found to possess a GRPR of identical molecular weight as that on Swiss 3T3 fibroblasts." (PMID 34539578, 2021). "In this study of GRP, immunoreactivity was also detected in 73% of the neuroblastomas, but in contrast to the GRPR, its expression was not affected by the tumor histology." (PMID 34539578, 2021). "In one study, neither the expression level of GRP mRNA nor GRPR mRNA in the neuroblastoma tissue correlated with prognosis." (PMID 34539578, 2021). "Evidence also suggests that PI3K/Akt is activated downstream of Gastrin-Releasing Peptide (GRP)/Gastrin-Releasing Peptide Receptor (GRPR) and Brain-derived neurotrophic factor (BDNF)/TrkB signaling, which are reported to be overexpressed in human neuroblastoma." (PMID 26793165, 2015). "In another study, in tissues from 19 neuroblastomas, all had GRP mRNA and GRPR mRNA detected, although neither the amount of GRPR nor GRP mRNA correlated with prognosis." (PMID 34539578, 2021). "No dual-labeled tracers, which enable both fluorescence visualization, and radioactivity-based depth of detection are FDA-approved and those in clinical trials target carbonic anhydrase IX, gastrin-releasing peptide receptor, and CEA, which are not as uniformly and highly expressed in neuroblastoma." (PMID 39407274, 2024). "However, in another study, the level of expression of GRPR mRNA, but not the amount of GRP mRNA, correlated with the histology of the neuroblastoma, with undifferentiated tumors having greater expression." (PMID 34539578, 2021). "In IMR-32 neuroblastoma cells, GRP did not stimulate changes in cytosolic calcium, although it stimulated growth in these cells, suggesting both Ca2+-dependent and Ca2+-independent pathways may mediate the growth effects of GRPR activation in different neuroblastoma cells." (PMID 34539578, 2021).